RIPK3 (receptor interacting serine/threonine kinase 3)
Diseases named in the same sentence as RIPK3 in open-access papers (continued):
Sharing a sentence is not in itself a finding about the gene and the disease.
infection (continued). "Strikingly, five days post-infection, we found a significant defect in the percentage of TNF and IL-6 positive Ripk3-/-Casp8-/- inflammatory monocytes isolated from the mesenteric lymph nodes (mLN) of mixed BM chimeras compared with either wild-type or Ripk3-/- cells from the same animal." (PMID 27737018, 2016). "However, what appeared to be the 17 kDa RIPK3 cleavage product (because it was detected in WT but not Ripk3D333A/D333A BMDMs) was detected after infection with ΔM36 MCMV, ΔM36, M45mutRHIM MCMV, or M45mutRHIM MCMV (compare lanes 3, 4 and 5 with lanes 8, 9, and 10)." (PMID 38191748, 2024). "Importantly, the transfer of Ripk3−/− MAIT cells mirrored the expected WT MAIT cell transfer phenotype, as transferred Ripk3−/− or WT MAIT cells equally conferred protection from weight loss and significantly increased survival time post infection compared to the no transfer group." (PMID 36774342, 2023). "Interestingly, the levels of the phosphorylated forms of RIPK1, RIPK3, and MLKL, the major signaling molecules in the RIPK1-dependent necroptosis pathway, were observed as early as 4 hpi and continuously increased to 20 hpi in response to infection with both RVA strains." (PMID 34668777, 2022). "In contrast to infection with ΔospD3, infection with ΔospD3ΔospI did not increase the levels of phosphorylated MLKL, RIPK1, and RIPK3, and cytotoxicity." (PMID 40931196, 2025). "In contrast to infection with ΔospD3, infection with ΔospC1ΔospD3ΔospI did not increase the levels of phosphorylated MLKL, RIPK1, and RIPK3, and cytotoxicity." (PMID 40931196, 2025). "PAMs without any treatment (MOCK) were used as the negative control, and IFN-β-stimulated PAMs were used as infection-free controls expressing ZBP1 and RIPK3." (PMID 38952452, 2024). "Western blot results revealed that the expression of ZBP1, p-RIPK3, and p-MLKL in PTCs cells infected with UV-inactivated PPV did not increase with prolonged infection time, unlike in cells infected with the non-irradiated virus." (PMID 39614405, 2024). "Surprisingly, transcriptional analysis revealed that pharmacologic blockade of RIPK3 did not influence the expression of the type I IFN ligands Ifna and Ifnb in cerebellar granule cell neurons following infection." (PMID 38011306, 2023). "On the other hand, Ripk3 mRNA (and not MLKL) is upregulated after certain infections (such as: Mycobacterium Tubercolosis and Clostridium difficile), independent of interferon signalling, via mechanisms that involve promoter demethylation." (PMID 36175538, 2023). "All Ripk3−/−Fadd−/− DKO mice died after the challenge, none of them being able to recover from infection-induced morbidity compared to the control mice." (PMID 33976111, 2021). "Mice lacking caspase-8, RIPK3, and RIPK1 (apoptosis/necroptosis) survived infection similarly to mice lacking either RIPK3 or MLKL, suggesting pyroptosis primarily protects against B. thailandensis in pyroptosis-competent mice." (PMID 34154417, 2021). "Infection with VV expressing a truncated E3L lacking this z-DNA binding domain led to increased ZBP1 expression and excessive Type I IFN-induced RIPK3/MLKL-dependent necroptosis." (PMID 30050058, 2019). "However, consistent with our previous studies, HCMV stimulation of RIPK3 activity does not phosphorylate and activate MLKL, which is dependent on the induction of autophagy following infection." (PMID 41190811, 2025). "However, RIPK3 did not affect the homeostasis and abundance of MAIT cells during infection with Francisella tularensis." (PMID 38684668, 2024). "Consistent with this, receptor-interacting kinase 3 (RIPK3), the kinase phosphorylating MLKL, was markedly phosphorylated in N2aC24 cells, but not in N2aC24L1-3 cells, after IAV/WSN infection, indicating that RIPK3 is activated in N2aC24 cells, but not in N2aC24L1-3 cells, after IAV/WSN infection." (PMID 39194237, 2024).
infection (continued). "Ripk3D333A/D333A macrophages died at the same rate as wild-type (WT) macrophages in response to TNF plus cycloheximide, TNF plus emricasan, or infection with murine cytomegalovirus (MCMV) lacking M36 and M45 to inhibit caspase-8 and RIPK3 activation, respectively." (PMID 38191748, 2024). "In addition, there was no significant increase in the relative levels of receptor interacting serine/threonine kinase 3 (RIPK3) expression in A549 and LLC cells following ORFV NA1/11 infection, compared to control cells (data not shown)." (PMID 35959371, 2022). "Interestingly, we found that viral titers at 12 and 24 hpi were both increased in PK-15 cells with RIPK3 or MLKL gene knockdown, independent of the multiplicity of infection (MOI) of PRV infection." (PMID 34149651, 2021). "Infection with E. coli in the absence or presence of GSK′872 did not result in macrophage death; however, we measured decreased viability following caspase inhibition, which was rescued by RIPK3 inhibition." (PMID 33024046, 2020). "However, perhaps not surprisingly, given the absence of a phenotype in Ripk3−/− mice, we found that neither the conditional deletion of Bcl-xL in myeloid cells nor the pharmacologic inhibition of BCL-XL after infection imparted any benefit to mice in terms of reduced bacterial burden." (PMID 29892302, 2018).
bacterial infection (11 papers, 2014 to 2025). "Our study suggests that Casp8 is dispensable for homeostatic hematopoiesis in young adult mice but is essential in preventing Ripk3-mediated necroptosis during bacterial infections or inflammations." (PMID 38637559, 2024). "The significantly delayed cell death and extensive cell-cell fusion observed in B. thailandensis-infected Casp8/Ripk3/Casp1/11−/− BMDMs suggested that bacterial infection is poorly controlled in these cells compared to WT." (PMID 34154417, 2021). "Therefore, we suggest that RIPK3 is a potential therapeutic candidate for bacterial infection‐induced pulmonary inflammation." (PMID 36226560, 2022). "In conclusion, by modulating the RIPK3-MLKL-mediated necroptosis, CDK9 inhibition provided a novel mechanism to impact the progress of bacterial infection in the periodontal milieu." (PMID 31758083, 2019). "However, to counteract the host response to bacterial infection, Shigella employs OspD3 to target and cleave the RHIM domains of RIPK1 and RIPK3, thereby degrading RIPK1 and RIPK3 and inhibiting necroptosis in host cells." (PMID 38933265, 2024). "In our present study, CDK9 inhibition or knock-down significantly reduced RIPK1, RIPK3 and TRIF levels after bacterial stimulation, thereby may reduce necroptosis during bacterial infection." (PMID 31758083, 2019).
inflammation (11 papers, 2015 to 2025). Aberrant reaction of the microcirculation characterized by movement of fluid and leukocytes from the blood into extravascular tissues. "Moreover, CCN2-induced kidney inflammation was prevented in RIPK3-deficient mice, indicating the key role of necroptosis in the inflammation induced by CCN2." (PMID 37627536, 2023). "Together, the results above demonstrated that Nrf2 deficiency could promote cardiac inflammation, RIPK3 expression and mitochondrial disorder in PM2.5-exposed mice." (PMID 32182211, 2020). "To clarify the contribution of necroptosis to IL-1α production in a mouse model of respiratory inflammation, we analyzed immune responses in the lungs of WT, Ripk1DN/DN, or Ripk3−/− mice following airway administration of emricasan." (PMID 41429777, 2025). "We found that RIPK3 expression had an inhibitory effect on UPM-induced airway inflammation and TEER." (PMID 37686124, 2023). "RIPK3-mediated epithelial necroptosis can lead to intestinal inflammation, and the lack of RIPK3 was shown to prevent skin inflammation in mice." (PMID 35422802, 2022).
neurodegenerative disease (9 papers, 2018 to 2025). A disorder of the central nervous system characterized by gradual and progressive loss of neural tissue and neurologic function. "RIPK3-dependent necroptosis has been associated with ischemic injury, inflammation, and neurodegenerative diseases." (PMID 38684668, 2024). "Both RIPK3 and its downstream target, MLKL, are key players in this machinery, which is a cornerstone of neurodegenerative diseases." (PMID 36242717, 2023). "Regulated necrosis or necroptosis, mediated by receptor-interacting kinase 1 (RIPK1), RIPK3 and pseudokinase mixed lineage kinase domain-like protein (MLKL), contributes to the pathogenesis of inflammatory, infectious and degenerative diseases." (PMID 32123582, 2020). "Necroptosis is an emerging field closely related to apoptosis and targeting RIPK3 and RIPK1 may help to overcome therapeutic hurdles in the treatment of inflammatory and neurodegenerative diseases." (PMID 29980212, 2018).
adenocarcinoma (5 papers, 2015 to 2023). A common cancer characterized by the presence of malignant glandular cells. "In subgroup analyses according to histology, CHIP(−)/RIPK3(+) was associated with shorter OS (HR 2.096, 95% CI 1.234–3.561, p = 0.006) and showed a trend toward shorter OS (HR 1.456, 95% CI 0.936–2.267, p = 0.096) in adenocarcinoma." (PMID 32521727, 2020). "These tumors displayed dysplastic lesions that progress from low- to high-grade dysplasia, and in some Ripk3−/− mice give rise to intra-mucosal adenocarcinomas." (PMID 27344176, 2016). "Interestingly, in TCGA Colorectal and Kaiser Colorectal datasets, RIPK3 was decreased in adenocarcinomas from different anatomical locations involving the cecum, colon, and rectum." (PMID 27344176, 2016). "Moreover, all HPV16-positive cervical SCC and 1 out of 2 HPV16-positive adenocarcinomas expressed RIPK3 in situ." (PMID 25888634, 2015). "In subgroup analyses according to histology, highly positive RIPK3 expression was associated with lower OS (HR 1.864, 95% CI 1.035–3.360, p = 0.038) and DFS (HR 1.775, 95% CI 1.051–2.999, p = 0.032) but not for CHIP in adenocarcinoma." (PMID 32521727, 2020). "Interestingly, 3 of 5 RIPK3-negative adenocarcinomas were also HPV-negative." (PMID 25888634, 2015).
kidney (5 papers, 2019 to 2025). "In vivo studies using Ripk3- or Mlkl-deficient mice validated kidney ischemia reperfusion injury and high-dose tumor necrosis factor (TNF) availability, as druggable targets in necroptotic-mediated pathologies." (PMID 30842945, 2019). "In kidney injuries, miR-500a-3p is thought to mitigate the toxicity and ischemic damage caused by necroptosis and inflammatory responses by targeting the MLKL and RIPK3 proteins according to experiments in HK2 cells." (PMID 36991314, 2023). "Nevertheless, there are also studies indicating that Mlkl deficiency confers less protection in the kidney IRI model compared to Ripk3 deficiency, and in contrast to Ripk3-deficient mice, Mlkl-deficient mice resemble wild-type mice in their sensitivity to hypothermia induced by low-dose TNF." (PMID 30842945, 2019).
cardiovascular diseases (4 papers, 2020 to 2024). "Ca2+/calmodulin-dependent protein kinase (CaMKII) is a newly discovered RIPK3 substrate, and its alternative splicing plays a fundamental role in cardiovascular diseases." (PMID 37833985, 2023). "In this review, we provide an overview of the current evidence supporting a pathologic role of RIPK1 and RIPK3 in cardiovascular disease." (PMID 33142926, 2020). "As observed in other cardiovascular diseases, a pro-inflammatory role for RIPK3 was demonstrated in AAA." (PMID 33142926, 2020). "Research into the role of RIPK1 and RIPK3 in cardiovascular disease and the potential to translate inhibitor studies from the bench to the bedside must continue to be aggressively pursued." (PMID 33142926, 2020). "Moreover, we highlight the evidence behind the efficacy of targeted RIPK1 and RIPK3 inhibitors in the prevention and treatment of cardiovascular disease." (PMID 33142926, 2020). "Specifically, the damaging role of two kinase proteins pivotal in the necroptosis pathway, Receptor Interacting Protein Kinase 1 (RIPK1) and Receptor Interacting Protein Kinase 3 (RIPK3), in cardiovascular disease has become a subject of great interest and importance." (PMID 33142926, 2020).
infectious disease (4 papers, 2022 to 2024). A disorder directly resulting from the presence and activity of a microbial, viral, or parasitic agent in humans. "Manipulating RIPK3/MLKL-mediated necroptosis may represent novel therapeutic targets, not only for RAP but also for other E. faecalis-associated infectious diseases." (PMID 35708336, 2022).
neurological diseases (4 papers, 2021 to 2024). "RIPK3 signaling has previously been shown to drive pathogenic neuroinflammation and neuronal cell death in several models of neurological disorders." (PMID 38713518, 2024). "Although RIPK3-dependent necroptosis has been implicated in several neurological disorders, RIPK3 also appears to promote neuroinflammatory processes via necroptosis-independent mechanisms, including the coordination of inflammatory transcription in multiple CNS cell types." (PMID 38713518, 2024). "Ripk3-/- mice exhibited enhanced neurologic disease following subcutaneous LGTV infection, while Mlkl-/- mice were indistinguishable from littermate controls, suggesting a necroptosis-independent function for RIPK3 in restricting LGTV pathogenesis." (PMID 38011306, 2023). "RIPK1, RIPK3, and MLKL play a pivotal role in inducing necroptosis, and RIPK1, RIPK3, and MLKL upregulation could be common in many neurological diseases, including CIR injury." (PMID 34905731, 2021).
heart diseases (3 papers, 2021 to 2022). "Moreover, receptor interacting protein kinase 3 (RIPK3)-mediated necroptosis is also involved in the pathological process of various heart diseases." (PMID 35571197, 2022).
respiratory diseases (3 papers, 2020 to 2023). "Our data indicate that the RIPK3 protein is critical for the regulation of the LPS‐induced inflammatory microenvironment in respiratory diseases." (PMID 36226560, 2022). "The biochemical and physiological mechanism by which actin remodelling and trans‐epithelial electrical resistance (TEER) may be affected by RIPK3 during P. aeruginosa infection in respiratory diseases remains unclear." (PMID 36226560, 2022).
immune disorders (2 papers, 2022 to 2023). "Accordingly, deletion of RIPK3 to some extent rebalanced the immune disorders in both LN and spleen including B cells (B220+) as well as myeloid cells (CD11b+)." (PMID 36721037, 2023).
animal disease (1 paper, 2022). "Therapeutically, the inhibition of RIPK3 or RIPK1 exhibited anti-inflammatory effects in animal disease models, suggesting that the inhibitors of these kinases may have a therapeutic potential to treat inflammatory injuries." (PMID 35769473, 2022).
bone disorder (1 paper, 2021). "In this study, we found that the RIPK1/RIPK3/MLKL pathway was involved in alcohol-induced bone disorders and osteoblast necroptosis both in vivo and in vitro." (PMID 34745415, 2021).
central nervous system diseases (1 paper, 2020). "Receptor interacting serine/threonine-protein kinase 3 (RIPK3) has been reported to contribute to neuroinflammation and neuronal death in many central nervous system diseases." (PMID 32265853, 2020).
movement disorder (1 paper, 2024). Neurological conditions resulting in abnormal voluntary or involuntary movement, which may impact the speed, fluency, quality and ease of movement. "Transcriptomic profiling revealed that astrocytic RIPK3 promoted gene expression associated with neuroinflammation and movement disorders, and this coincided with significant engagement of damage-associated molecular pattern signaling." (PMID 38713518, 2024).
RIPK3 also shares sentences with these, for which no sentence is quoted: multiple sclerosis (4 papers); acute myocardial infarction (3); hypertrophy (3); acute liver failure (2); atrial fibrillation (2); chronic periodontitis (2); colorectal adenocarcinoma (2); cutaneous melanoma (2); Dry skin (2); Encephalopathy (2); Granuloma (2); histiocytic lymphoma (2); hypoxia (2); metabolic disorders (2); metabolic syndrome (2); retinitis (2); Shock (2); small cell lung carcinoma (2); subarachnoid hemorrhage (2); acute monocytic leukaemia (1); acute tubular necrosis (1); adenosquamous carcinoma (1); Age-Related Hearing Loss (1); age-related macular degeneration (1); alcohol (1); alcoholic hepatitis (1); alcoholic liver diseases (1); Atherosclerotic lesion (1); atrial fibrillation and flutter (1); atrial septal defect (1).
A further 75 diseases each share a sentence with RIPK3 in 1 paper.